KDM6B (lysine demethylase 6B)
Diseases named in the same sentence as KDM6B in open-access papers (continued):
Sharing a sentence is not in itself a finding about the gene and the disease.
postmenopausal osteoporosis (1 paper, 2022). Metabolic disorder associated with fractures of the femoral neck, vertebrae, and distal forearm. "Therefore, the identification of KDM6B regulatory mechanisms, such as miR-99a and miR-146a, during estrogen-induced osteogenesis may lead to targeted therapeutic approaches for postmenopausal osteoporosis." (PMID 34992221, 2022).
prostate adenocarcinoma (1 paper, 2022). "Most prostate adenocarcinoma cases with genetic changes had an altered copy number deletion of KDM6B (∼4% frequency)." (PMID 35783266, 2022).
pterygium (1 paper, 2022). A wedge-shaped fibrovascular lesion arising from the bulbar conjunctiva and extending to the cornea. "Furthermore, we have found that the expression of multiple epigenetic regulators was upregulated in the 3D pterygium model, including DNA methyltransferase DNMT3B, lysine demethylase KDM6B, and histone deacetylase HDAC5." (PMID 35101743, 2022).
visceral leishmaniasis (1 paper, 2025). A severe form of leishmaniasis characterized by irregular bouts of fever, substantial weight loss, swelling of the spleen and liver, and anemia (which may be serious). "In earlier study, they demonstrated that the functional knockdown of KDM6B in an experimental model of visceral leishmaniasis led to a substantial reduction in the parasite burden within infected organs." (PMID 40898518, 2025).
tumor (128 papers, 2012 to 2026). "Many studies have demonstrated that KDM6B is positively or negatively associated with tumor progression." (PMID 40959109, 2025). "In certain cancer types, such as neuroblastoma, hepatocellular carcinoma, lung adenocarcinoma, and endometrial cancer, KDM6B functions as a tumor suppressor, and its expression is associated with improved survival rates and prognoses." (PMID 39620228, 2024). "Spearman correlation analysis was used to assess the association of the KDM6B expression with TMB (tumor mutation burden) and MSI (microsatellite instability)." (PMID 35783266, 2022). "More importantly, a large body of data has shown the association of KDM6B abnormality with tumor progression." (PMID 34165914, 2021). "Aberrant epigenetic factor lysine‐specific demethylase 6B (KDM6B) has been associated with tumor progression." (PMID 34165914, 2021). "KDM6B is downregulated in high-risk neuroblastomas, and functions as a tumor suppressor through neuronal differentiation by activating NEFM." (PMID 34950587, 2021). "While KDM6A is believed to be a tumor suppressor and is mutated in many different types of cancer, the function of KDM6B in cancer remains poorly defined." (PMID 34893606, 2021). "Regional glutamine deficiency decreases KDM6B expression, which promotes tumor heterogeneity and therapeutic resistance." (PMID 34950587, 2021). "In addition, we detected a significantly positive association between the KDM6B expression and tumor-associated fibroblast infiltration levels in tumors of BRCA, HNSC−HPV−, LIHC, LUAD, OV, PAAD, SKCM, and SKCM−Metastasis from TCGA." (PMID 35783266, 2022). "KDM6B was associated with multiple immune cells, suggesting that KDM6B may affect the progression and clinical outcomes of tumors via the tumor microenvironment." (PMID 35783266, 2022). "While many studies demonstrate the mutations of KDM6A and KDM6B in cancers and suggest a tumor-suppressive function of these two demethylases, several studies show KDM6A and KDM6B may exhibit oncogenic activity." (PMID 28717873, 2018). "In particular, our data highlighted the importance of KDM6B in HCC malignancy and functions of LCSCs because the tumor-initiating ability of LCSCs was reduced by KDM6B deficiency, and the JIB-04-induced elevation of H3K27me3 levels could be reduced by the demethylase activity of KDM6B." (PMID 35887001, 2022). "Notably, the tumor cell-restricted cytotoxicity of TCRαβ+CD8αα+ IELs was significantly attenuated by the loss of Kdm6b, thus resulting in defective immune surveillance in Kdm6b-deficient mice." (PMID 34999729, 2022). "Another example is presented here: miR-138-5p delivered by tumor exosomes was found to target KDM6B (JMJD3) in macrophages, thereby upregulating H3K27me3 and blunting an M2-to-M1 reprogramming attempt." (PMID 40358164, 2025). "Intestinal epithelial-specific KDM6B deletion promotes tumor growth by increasing MDSCs-mediated immunosuppression." (PMID 41387297, 2025). "Targeting the Hmox1/iron/Kdm6b signaling pathway in FerroCAFs was shown to enhance anti-tumor immunity and suppress tumor growth in experimental models." (PMID 40649958, 2025). "The results showed that KDM6B overexpression significantly reduced the tumor volume, tumor weight and the liver metastatic area in CRC." (PMID 40959109, 2025). "Correspondingly, IHC staining showed that the expression of PD-L1 increased in tumor tissues overexpressing KDM6B compared to that in the control group." (PMID 40959109, 2025). "On the other hand, KDM6B was found to mediate the promoting effect of epithelial cell adhesion molecule (EpCAM) on tumor proliferation in CRC15." (PMID 40959109, 2025). "KDM6B KO cells had slower tumor growth and an increase in survival from 18.5 days in the control group to 30 and 33 days in sgKDM6B#1 and sgKDM6B#2, respectively." (PMID 41085408, 2025). "KDM6B acts as a tumor suppressor in M2/M3 AML, where its downregulation blocks differentiation and is associated with poor prognosis." (PMID 39680456, 2024).
tumor (continued). "Similar to GSK-J4, KDM6A/ KDM6B-knockdown minimally effected basal tumor growth but dramatically potentiated the effects of cisplatin, again with evidence of tumor regression, and all mice remained tumor-free for over 90 days after a single dose of cisplatin." (PMID 39482699, 2024). "We validated KDM6A/KDM6B as the target of GSK-J4 since KDM6A/KDM6B genetic depletion had a similar effect to GSK-J4 on cisplatin-mediated anti-tumor activity and transcriptome alterations." (PMID 39482699, 2024). "We validated KDM6A/KDM6B as the target of GSK-J4 since KDM6A/KDM6B genetic depletion had a remarkably similar effect to GSK-J4 on cisplatin-mediated anti-tumor activity and transcriptome alterations." (PMID 39482699, 2024). "Despite its tumor-suppressive functions, KDM6B can also act as an oncoprotein in certain contexts, promoting tumor progression." (PMID 39620228, 2024). "GSK-J4 suppresses the KDM6B-mediated proinflammatory response in macrophages, reduces tumor volume in mice xenografts of an ovarian cancer model, and reduces T-ALL xenograft growth in a mouse model." (PMID 36975603, 2023). "In summary, this study assessed the dual role of KDM6B in tumor progression and clinical outcomes across all types and stages of cancers in TCGA for the first time." (PMID 35783266, 2022). "In various types of malignancies, KDM6A predominantly serves a tumour suppressor role, whereas KDM6B functions as an oncogenic protein." (PMID 35915507, 2022). "KDM6B has been shown to be involved in tumor progression via the regulation of cell proliferation, migration, and senescence." (PMID 36233212, 2022). "Little experimental support exists for the specific mechanism of KDM6B in tumor progression and immune cell infiltration." (PMID 36713412, 2022). "Previous studies have shown that KDM6B has a dual role in different tumor settings, by acting as a tumor suppressor and an oncogene." (PMID 36564369, 2022). "With the GEPIA2 tool, we pooled all TCGA tumor expression data to gain the top 100 genes related to the KDM6B expression." (PMID 35783266, 2022). "Tumor-derived exosomal miR-138-5p was able to regulate TAM polarization by inhibiting lysine demethylase 6B (KDM6B), suppressing the M1 phenotype, and promoting M2 macrophages." (PMID 36362044, 2022). "The KEGG (Kyoto encyclopedia of genes and genomes) pathway analysis and GO (Gene ontology) enrichment analysis were used to further investigate the potential mechanism of KDM6B in tumor pathophysiology." (PMID 35783266, 2022). "To explore the potential mechanisms of KDM6B in tumor pathophysiology, we sought to highlight KDM6B-binding proteins and KDM6B expression-related genes in several pathway enrichment analyses." (PMID 35783266, 2022). "Although immunotherapy has shown increasing the therapeutic impact in tumors, we barely obtained any reports focusing on the relationship between the KDM6B expression and tumor immunity through literature search." (PMID 35783266, 2022). "In terms of events possibly influencing primary tumor development, Lysine (K)-Specific Demethylase 6B (KDM6B) caught our attention given its role as an epigenetic regulator and a histone methylation modifier." (PMID 33827048, 2021). "Here we show that miRNA-138-5p derived from tumor cells influences the expression and activity of the critical epigenetic regulator KDM6B in macrophages and thus influences macrophage polarization." (PMID 34093857, 2021). "and analysis of the adjacent non-tumor esophageal tissues and ESCC tissues by IHC revealed that KDM6B expression is associated with the lymph node metastasis and the N stage of ESCC, but not with age, sex, T stage or Pathologic differentiation." (PMID 34001062, 2021). "Because EMT is an important process during tumor metastasis, we subsequently tested the regulatory effect of KDM6B on EMT markers." (PMID 34165914, 2021). "In several cancers, KDM6B is downregulated and regarded as a tumor suppressor by counteracting different transcriptional programs." (PMID 34950587, 2021).
tumor (continued). "KDM6B is upregulated or downregulated by different signaling pathways, and play essential roles in the tumor microenvironment." (PMID 34950587, 2021). "More and more studies have shown that KDM6B can be used as a biomarker and therapeutic target for tumor diagnosis and prognosis." (PMID 34001062, 2021). "We assessed tumor cell proliferation in response to KDM6B interference or overexpression, using the CCK-8 assay." (PMID 34001062, 2021). "To evaluate the impact of KDM6B on tumor growth and dissemination in vivo, we used an orthotopic xenograft mouse model." (PMID 34165914, 2021). "Recently, the mechanisms of KDM6B in regulating inflammatory genes have been studied extensively and deeply, supporting the view that KDM6B involves the engagement of an inflammatory tumor microenvironment." (PMID 34950587, 2021). "To further investigate the effect of KDM6B on tumor metastasis, we performed pulmonary metastasis assay in nude mice by injecting sh-KDM6B-1 and sh-NC transfected KYSE150 cells through the tail vein." (PMID 34001062, 2021). "Lysine (K)-specific demethylase 6B (KDM6B), a stress-inducible H3K27me3 demethylase, plays oncogenic or antitumoral roles in malignant tumors depending on the type of tumor cell." (PMID 33414463, 2021). "We examined tumor volume over time and observed that KDM6B interference significantly repressed tumor growth rates and decreased tumor weight." (PMID 34001062, 2021). "In our study, we found that KDM6B regulates glycolysis in tumor cells via modulating lactate dehydrogenase A expression, and then affect the progress of OS." (PMID 33664867, 2021). "In hepatocellular carcinoma, KDM6B is highly expressed and positively corelated with distant metastasis, tumor diameter, vascular invasion, differentiation, and poor prognoses in patients." (PMID 33003334, 2020). "We next explored the mechanism by which KDM6B inhibits tumor progression." (PMID 40959109, 2025). "Another tumour demonstrated partial KIAA1549 inversion in addition to CDK4 and KDM6B variants." (PMID 39948623, 2025). "In this study, we found that KDM6B expression is downregulated in tumor tissues and cell lines." (PMID 40959109, 2025). "While KDM6A and KDM6B have a tumor suppressor role, other members of the KDM family like KDM2B, KDM3A, and KDM5A may serve as oncogenes in PDAC." (PMID 38791111, 2024). "In addition, KDM6B acts as a tumor suppressor in PC by demethylating histone H3 lysine 27, thereby controlling the expression of CEBPA, a key gene associated with cancer progression." (PMID 39239542, 2024). "KDM6B functions as both a tumor suppressor and an oncogene, depending on the cellular context." (PMID 39620228, 2024). "The dramatic in vivo effects, as compared to in vitro effects of GSK-J4 and KDM6A/KDM6B-knockdown, suggest that host and/or tumor microenvironment contributions may be occurring during cisplatin sensitization." (PMID 39482699, 2024). "Thus, KDM6B plays dual roles in cancer, acting as either a tumor suppressor or an oncogene, depending on the specific cancer type and context." (PMID 39620228, 2024). "Research on the role of KDM6B in cancer has primarily demonstrated the role of this enzyme as a tumor promotor, through the function of this enzyme is context-dependent, as this enzyme mediates bother carcinogenic and anti-cancer signaling pathways (reviewed by Hua and colleagues)." (PMID 35625569, 2022). "The observation of KDM6B downregulation across cancer types was consistent with prior knowledge that KDM6B could regulate the expression levels of specific genes and the interactions of protein molecules contributing to tumor suppression." (PMID 35783266, 2022). "The evidence suggests the potential role KDM6B plays in the tumor immunity." (PMID 35783266, 2022). "We detected a genetic change of KDM6B in several tumor cases from TCGA projects with cBioPortal." (PMID 35783266, 2022).
tumor (continued). "Moreover, we also predicted that the KDM6B expression level was correlated with the tumor immune microenvironment." (PMID 35783266, 2022). "In addition, we explored the KDM6B protein expression in the cohort of the Human Protein Atlas database across 20 different tumor types." (PMID 35783266, 2022). "Lysine demethylase 6b (KDM6B) is essential for the generation and proper functioning of CD8+ effector T cells during acute infection and tumor eradication, being indispensable for proper effector functions and tumor protection, and KDM6B inhibition exhibits a memory-defective T cell response." (PMID 36233212, 2022). "On the contrary, KDM6B can also serve as a tumor suppressor." (PMID 35783266, 2022). "This study elucidates a new epigenetic regulation mechanism in which KDM6B regulates tumor metastasis by directly mediating H3K27me3 demethylation of the glycolysis-related gene LDHA, thereby leading to increased LDHA expression and facilitated tumor metastasis in OS." (PMID 33664867, 2021). "However, KDM6B is a proposed tumor suppressor in oncogene‐induced senescence, colorectal cancer and pancreatic ductal adenocarcinoma." (PMID 34165914, 2021). "As LDHA executes aerobic glycolysis in tumor cells by catalyzing the conversion of pyruvate to lactate, to determine the metabolic effects of KDM6B silencing in OS cells, we calculated the aerobic glycolysis index in control and KDM6B-KD OS cells." (PMID 33664867, 2021). "As shown for other KDMs, whether KDM6B functions as an oncogene or as a tumor suppressor is strongly disease stage and cell lineage dependent." (PMID 34944554, 2021). "Moreover, similar to KDM6A, KDM6B expression is also subjected to different levels of its cosubstrates from cellular metabolism and tumor microenvironments." (PMID 34950587, 2021). "Similarly, knockdown of KDM6B reduces tumor growth and induces apoptosis in diffuse large B-cell lymphoma." (PMID 33003334, 2020). "In addition, KDM6A/KDM6B knockdown or upregulation of H3K27me3 levels sensitized OS to cisplatin by enhancing apoptosis in tumor cells." (PMID 30651137, 2019). "Collectively, our results indicated that KDM6A or KDM6B knockdown could sensitize OS to cisplatin by enhancing apoptosis of tumor cells." (PMID 30651137, 2019). "However, a subsequent study showed that KDM6B is required for the initiation and maintenance of T-ALL, while KDM6A acts as a tumor suppressor in T-ALL and is frequently mutated in this cancer." (PMID 28717873, 2018). "Here the tumor suppressive properties of KDM6B were also suggested to be demethylase-independent." (PMID 30619733, 2018). "Secondly, modulating KDM6B may help overcome tumor immune evasion." (PMID 40959109, 2025). "Importantly, single-cell RNA-sequencing (sc-RNA-seq) data demonstrated that surgical removal of the tumor increased antigen-presenting dendritic cell population with a concurrent reduction in KDM6B-expressing immune-suppressive myeloid cells in the peripheral blood." (PMID 39606482, 2024). "Thus, the balance of the KDM6B levels is important for normal hematopoiesis and tumor suppression." (PMID 37917239, 2024). "KDM6B inhibition with GSK-J4 may consequently dampen down anti-tumour cytotoxic T cell responses." (PMID 35915507, 2022). "However, KDM6B is more frequent upregulated and functions as tumor promotor in various cancers." (PMID 34950587, 2021). "However, it has also been reported that KDM6B appears as a suppressor gene in tumor." (PMID 34001062, 2021). "Interestingly, a positive feedback loop is found between KDM6B and BMP signaling, and KDM6B also could employs BMP and NF-kB pathways to modulate the tumor microenvironment by angiogenesis and tumor associated-macrophage infiltration." (PMID 34950587, 2021).